NF1 (neurofibromin 1)
Diseases named in the same sentence as NF1 in open-access papers (continued):
Sharing a sentence is not in itself a finding about the gene and the disease.
cancer (622 papers, 2004 to 2026). A tumor composed of atypical neoplastic, often pleomorphic cells that invade other tissues. "In NF1-deficient tumors, PD-1 antibodies have been shown to improve survival in melanoma and other cancer types." (PMID 41541668, 2026). "A number of RAF inhibitors (RAFi) and MEK inhibitors (MEKi) are currently FDA approved for use in genomically selected cancers as well as Neurofibromatosis type 1 (NF1)-associated plexiform neurofibroma." (PMID 40634537, 2025). "From a practical, clinical point of view, it is conceivable that the extent of second NF1 hits in normal tissues represents a quantifiable link between germline genotype and cancer risk." (PMID 40000831, 2025). "In general, NF1 is associated with higher rates of benign and malignant tumors, and the life expectancy is 10–15 years shorter than that of the general population." (PMID 41022755, 2025). "NF1 somatic variants are rare in primary cancers; are associated with poor prognosis and increased risk of recurrence; have a high incidence of contralateral BC, poor survival, and BC progression; and contribute to endocrine therapy resistance." (PMID 40941673, 2025). "The role of NF1 status as a risk factor remains controversial in the literature, as RT in children with NF1, when applied below the age of ten years, increases the risk of death due to cerebrovascular accidents and secondary malignant tumors." (PMID 40075564, 2025). "Among the risks of benign and malignant tumors associated with NF1, the development of secondary malignancies following radiation therapy has become a subject of increasing clinical concern." (PMID 41216086, 2025). "NF1 germline mutation and the inactivation of this tumor suppressor gene, is known to predispose individuals to various cancers, including MPNSTs." (PMID 39857962, 2025). "The cancer-associated transcripts including NF1, ATM, MUC16, and KMT2C, were found at higher mRNA levels with ExCy." (PMID 40598203, 2025). "A population-based study from Finland reported a reduction in lifespan of about 16.5 years for men and 26.1 years for women with NF1, primarily due to the elevated risk of both benign and malignant tumors." (PMID 40428382, 2025). "NF1 is an autosomal dominant cancer predisposition caused by mutations in the NF1 gene resulting in the loss of the tumor suppressor neurofibromin, which is a negative Ras regulator." (PMID 41374983, 2025). "Individuals with NF1 mutations are predisposed to developing various malignant tumors, including BC." (PMID 41155378, 2025). "Additional cooperating mutations in known cancer genes (including Nf1, Ep300, Notch1, Sbds, and Ets1) were identified in 5 of the 9 GAB2 mAMLs." (PMID 40773291, 2025). "In NF1, the mutation deactivates neurofibromin protein, a tumor suppressor, causing the growth of malignant tumors on the optic nerve." (PMID 38540335, 2024). "The distinct age-profiles of NF1-associated cancer risk, and the cognitive and behavioral problems associated with NF1 are well known." (PMID 37460655, 2024). "As expected, the marked cancer predisposition associated with NF1 translated into significant excesses of reimbursed days of sickness absence and disability-related retirement." (PMID 37460655, 2024). "Instead, like other tumor suppressor genes, NF1 possesses a diverse mutational spectrum with over 13,000 unique somatic mutations reported in the Catalogue of Somatic Mutations in Cancer." (PMID 39472976, 2024).
cancer (continued). "The work presented here demonstrates that Y102 alters lysosome positioning and impacts mitochondrial clearance in NF1-deficient cancer cells and is synthetic lethal with NF1 loss in an isogenic yeast model." (PMID 39016685, 2024). "Our analysis of genes upregulated after the loss of the PRC2 in NF1-deficient iHSCs revealed the enrichment of several cancer-related pathways." (PMID 39620202, 2024). "Unfortunately, NF1 patients have a life expectancy 10–15 years shorter than the general population, thought to be at least in part due to increased risk of cancers with a poorer overall prognosis." (PMID 38543265, 2024). "For humans, the human ortholog NF1 has been shown that the gene is associated with multiple diseases, including cancer." (PMID 38475791, 2024). "Sophisticated fragmentomic analysis of cfDNA therefore has the potential to distinguish between non-cancer, pre-cancer, and cancer states and facilitate early cancer and pre-cancer screening for the most deadly malignancy associated with NF1." (PMID 38293154, 2024). "Of the 30 NF1 missense mutations detected in our cohort, seven were predicted to be cancer-promoting and the rest were predicted to be likely passenger mutations by FATHMM." (PMID 39472976, 2024). "In this cancer, only nine other genes appear to be recurrently mutated, including NF1 together with BRCA1, BRCA2, and RB." (PMID 37627552, 2023). "Despite progress in DNA sequencing technology for cancer diagnostics, our data suggest for identifying NF1 mutations, this approach is insensitive as in many cases NF1 is lost at the protein and mRNA levels without a clear genomic lesion." (PMID 37501682, 2023). "NF1 reduces average life expectancy by 15–10 years, and malignant tumors are the most common cause of death in individuals with this syndrome." (PMID 37789344, 2023). "NF1-deficient cells become tolerant to proteotoxic stress and, in animal models, HSF1 loss of function contrasts the development of NF1-related cancers by weakening oncogenic Ras/MAPK signaling." (PMID 37627552, 2023). "Germline NF1 inactivation causes neurofibromatosis type 1 (NF1), a relatively common autosomal dominant genetic disorder characterized by predisposition to cancer development." (PMID 36900287, 2023). "Unsurprisingly, NF1 is indeed somatically deficient in a variety of sporadic cancers, accounting for about 5–10% of all human malignancies." (PMID 37627552, 2023). "Via RAS inhibition, NF1 mutations affect multiple signaling pathways linked to cell survival and proliferation and the development of cancers." (PMID 38136356, 2023). "Since the somatic mutations of NF1 have been detected in various cancers, somatic mutations of NF1 in GBC were investigated." (PMID 37147639, 2023). "These syndromes exhibit multiple overlapping phenotypic features to NF1 including increased cancer risk." (PMID 37124503, 2023). "In the context of KRAS-mutant cancer, NF1 loss usually indicates overactivation of RAS and enhanced cell growth." (PMID 37355626, 2023). "Further study is needed to confirm these findings and assess the safety of high perigestational folic acid intake in the presence of cancer-susceptibility syndromes, particularly NF1." (PMID 37848948, 2023). "MPNSTs, which are frequently associated with either heritable or sporadic mutations in NF1, can result from prior radiation treatment and are malignant tumors with Schwann cell or perineural cell differentiation." (PMID 37173979, 2023). "The lifetime risk of cancer in patients with NF1 was estimated to be 59.6%, compared to 30.8% in the general population." (PMID 36684394, 2023). "According to a Finnish study, at the age of 50, NF1 has a cumulative cancer risk of 38% and a lifetime cancer risk of 59.6%." (PMID 37773168, 2023). "Since the population with NF1 already has an increased risk of developing cancer, limiting diagnostic radiation exposure in this population is recommended." (PMID 36684394, 2023).
cancer (continued). "A study in Finland reported that the cumulative cancer risk of 38% on NF1 carriers at age 50, and the lifetime cancer risk of 59.6%, which were 3.9% and 30.8% in the general population, respectively." (PMID 36620543, 2022). "It is likely that AgNPs induce damages similar to those observed in other cancers, and subsequent apoptosis and necrosis in NF1-associated MPNSTs." (PMID 35887576, 2022). "A wide range of benign and malignant tumors in both central and peripheral nervous systems, as well as other organ malignancies, has been described in association to NF1." (PMID 35885913, 2022). "We observed a homogenous tendency of all patients to display pathogenic mutations of the NF1 gene in circulating EVs as in matched cancer tissue." (PMID 36289852, 2022). "These tumors can arise sporadically but are often associated with the cancer-predisposing genetic condition, neurofibromatosis type 1 (NF-1)." (PMID 35891854, 2022). "Some events are shared between pediatric and adult HGG; for example, neurofibromin 1 (NF1) is mutated in 5% of all cancers and 10% of HGG3,4,9 However, the prognosis for both children and adults diagnosed with this devastating disease remains dismal." (PMID 35102191, 2022). "Malignant tumors that harbor pathogenic NF1 variants additionally to other genetic events show increased response when MEK inhibition is combined with other therapeutics." (PMID 33863389, 2021). "Even in NF1-associated malignant tumors such as in MPNST, multi-step mutational processes afford combination therapy." (PMID 33863389, 2021). "Neurofibromatosis type 1 (NF1) is a complex disorder characterized by a multisystem involvement and cancer predisposition." (PMID 33919865, 2021). "In 5.8% of survivors, pathogenic or likely pathogenic variants were detected in specific cancer predisposition genes, e.g., Rb1, NF1, BRCA2." (PMID 34680213, 2021). "A phase II study (NCT03872427) that was initiated to investigate the role of CB-839 HCl, a glutaminase inhibitor, in cancer cases with specific mutations, including NF1-mutation positive MPNSTs, is still ongoing." (PMID 34359780, 2021). "We only found a handful of enriched cancer genes, namely for Asian CCLs; NF1 mutations are more abundant for GBM (adj." (PMID 34576298, 2021). "In other words, the number of potential noncanonical and canonical RAS point mutations capable of promoting cancer was greater in the NF1-deficient context." (PMID 34065786, 2021). "Cancer-associated genes such as RB1, AML1, and CMYC, which display synchrony in allelic replication in normal cells, have shown earlier replication timing and asynchronous allelic replication in neurofibromatosis type 1 (NF1), a cancer-predisposing syndrome." (PMID 34831011, 2021). "Genotype–phenotype correlations also impact the cancer risk and the overall prognosis of NF1 patients." (PMID 33919865, 2021). "While molecularly targeted therapies are showing promise in clinical trials, surgery is still the mainstay of treatment for amenable NF1-associated benign and malignant tumors." (PMID 33669386, 2021). "They involved PD-0325901 (mirdametinib), trametinib, dabrafenib, and MEK162 (binimetinb) in phase 1 and 2 studies and included individuals with NF1-associated plexiform neurofibromas and other cancers harboring V600 mutations or RAS/RAF/MEK activated tumors." (PMID 33863389, 2021). "In support of this, the Onc2.3-driven cuSCCs also exhibited inactivation of Nf1, encoding a negative regulator of Ras signaling important in many cancer types." (PMID 33435458, 2021).
cancer (continued). "In this review, we discussed the molecular characteristics of MES GBM, NF1 gene mutation, and dysregulation in NF1-associated and non-NF1 associated cancers, particularly GBM." (PMID 35008787, 2021). "Due to its large size and complexity, NF1 is one of the most frequently mutated genes in men and in cancers." (PMID 35008787, 2021). "These class 2 (‘two-hit loss’) drivers include the genes RB1 (3/13 cancer types), NF1 (5/8), NF2 (1/2), PTEN (7/15), and BAP1 (2/6)." (PMID 34862370, 2021). "For patients with NF1, which is a hereditary and systemic disease associated with a high incidence of malignant tumors, it will be of great benefit when the number of such clinics in Japan and the rest of Asia is increased." (PMID 34099792, 2021). "Studies have shown that radiotherapy increased the incidence of second malignant neoplasms (SMNs) in patients with NF1 mutations." (PMID 33061844, 2020). "We also noticed that the NF1 mutation R1250Q seen in cancer patients is located at the NF1-SPRED1 interface." (PMID 32697994, 2020). "The NF1 stop gain mutation (c.7486C > T, p.Arg2496*, variant allele frequency 15.7%) was identified among the cancer-related genes listed in the Cancer Gene Census of COSMIC database." (PMID 33046013, 2020). "This has implications not only for NF1-associated tumors but in other cancers where mutation or overexpression of RAS genes occur, collectively known as RASopathies." (PMID 31906320, 2020). "SUZ12 loss potentiates the effects of NF1 mutations in NF1-associated cancers by amplifying Ras-driven transcription through enhancing acetylation at H3K27." (PMID 33374737, 2020). "Patients with NF1 have an increased cancer risk and mortality, and lower survival compared with the general population." (PMID 32650362, 2020). "Patients with NF1 are heterozygous for NF1 gene mutations, but the benign and malignant tumors that develop in these patients are caused, in part, by somatic cell loss of the remaining wildtype NF1 allele." (PMID 32353955, 2020). "NFIA (nuclear factor I A) encodes a member of the NF1 (nuclear factor 1) family of TFs known to act as oncogenes in several cancer models." (PMID 33371395, 2020). "To date, more than 3000 different germline mutations within the NF1 gene have been identified and shown to be pathogenic, but acquired somatic mutations in NF1 are also found in a wide variety of malignant neoplasms unrelated to NF1." (PMID 33121128, 2020). "SPRED1 and NF1 loss-of-function mutations occur across multiple cancer types and developmental diseases." (PMID 32697994, 2020). "Genetic alterations on the NF1 gene have often been reported in numerous cancer types, and mutation or deletion of NF1 was observed in 10% of GBM cases." (PMID 33053763, 2020). "Patients with RASopathy Neurofibromatosis 1 (NF1) are at a markedly increased risk of the development of benign and malignant tumors." (PMID 32650362, 2020). "The bioinformatics analysis identified two pathogenic variants in Fgfr4 and Nf1 genes, which are highly relevant for this type of cancer." (PMID 33231602, 2020). "In NF1 individuals, loss of Nf1 results in high levels of activated Ras, leading to the formation of multiple benign and malignant tumors via multiple effector pathways, including the Ras–MAPK pathway, with subsequent activation of the RAF–MEK–ERK cascade." (PMID 32650362, 2020). "Further, NF1 was mutated in as many as 54 cancer types with the highest frequency occurring in different types of melanomas." (PMID 31979111, 2020). "CRISPR/Cas9 engineered NF1 deficiency furthermore maintained cancer cell growth despite CET treatment." (PMID 31287991, 2019).
cancer (continued). "A study based in Finland showed an estimated lifetime cancer risk of 59.6% in patients who harbor NF1 gene mutation." (PMID 31507634, 2019). "These different miRNA profiles of NF1-associated PAs were previously related with known deregulated pathways in cancer, such as the cell cycle and hippo pathways, and suggest a distinct tumorigenesis process associated with miRNA dynamics in this PA subgroup." (PMID 31694342, 2019). "In the present study, we demonstrate that Y100 perturbs proteostasis, mitochondrial function, and mitochondrial superoxide in NF1-deficient cancer cells and is synthetic lethal with NF1 loss in a yeast model." (PMID 29662612, 2018). "The key negative regulatory gene of the RAS pathway, NF1, is mutated or deleted in a wide range of cancers and is increasingly recognized as a significant cancer driver." (PMID 30182054, 2018). "The Ras classifier’s performance predicting NF1 loss of function was comparable to that of distinct pan-cancer models trained specifically to detect NF1 loss-of-function events." (PMID 29617658, 2018). "We also identified several cancer-related genes affected by SF3B1-associated abnormal splicing: NF1, PDS5A, DICER1, and PML." (PMID 30194306, 2018). "Germline mono-allelic loss of the tumour suppressor NF1 predisposes patients to the development of benign lesions but rarely further progression into cancer development." (PMID 30479396, 2018). "Long before the discovery of mutations in SDHx in PPGL, the major genetic mutations associated with these cancers were of neurofibromatosis-1 (NF1), RET and von Hippel-Lindau (VHL)." (PMID 29450727, 2018). "The RAS/MAPK/AKT signaling pathways are a major target for cancer therapy, however the presence of NF1 mutations, which results in reduced expression of NF1, confers resistance to several therapeutic targets." (PMID 30131853, 2018). "Y100 treatment disrupted proteostasis, metabolic homeostasis, and induced the formation of mitochondrial superoxide in NF1-deficient cancer cells." (PMID 29662612, 2018). "It is true that NF1 patients have a higher lifetime risk of developing a cancer compared to the general population." (PMID 30479396, 2018). "Previously referred to as “malignant schwannoma” or “neurofibrosarcoma”, MPNST is the most common malignant tumour associated with NF1." (PMID 30187267, 2018). "Beyond the NF1 gene, cNFs are thought to have a low somatic mutation burden when compared with most cancers." (PMID 29695767, 2018). "The key negative regulatory gene of the RAS pathway, NF1, is mutated or deleted in numerous cancer types and is associated with increased cancer risk and drug resistance." (PMID 30182054, 2018). "The mutational landscape of somatic NF1 mutations should provide novel insights into our understanding of the pathophysiology of cancer." (PMID 28637487, 2017). "NF1 is an autosomal dominant condition that represents the most common human cancer genetic predisposition syndrome, affecting 1 in 3000 live births." (PMID 28622765, 2017). "Li reported that the germline mutations in NF1 that cause NF1 can also occur in somatic cells and contribute to the cancer development." (PMID 28835241, 2017). "The mutational landscape of somatic NF1 mutation should provide new insights into our understanding of the pathophysiology of cancer." (PMID 28637487, 2017). "The RAS/MAPK pathway, with an important role in cancer biology, is a prime target for anti-cancer agents; however, the presence of an NF1 mutation, resulting in reduced expression of neurofibromin, confers resistance to several therapeutic drugs." (PMID 28637487, 2017).